CD163 (CD163 molecule)
Diseases named in the same sentence as CD163 in open-access papers (continued):
Sharing a sentence is not in itself a finding about the gene and the disease.
bladder cancer (20 papers, 2015 to 2026). "Macrophage regulation and balance is critical for cancer outcome, and, in bladder cancer, CD163 has been associated with poor prognosis." (PMID 34209558, 2021). "To address this controversy, we performed this meta-analysis based on the TAMs identified by CD68 and CD163 markers to evaluate the potential association between TAMs density and prognostic outcomes in bladder cancer." (PMID 29861872, 2018). "Subgroup analysis was performed with regard to the instillation drugs used after TUR, and the pooled results indicated that the high CD163+ TAMs density was associated with poor RFS in the bladder cancer patients treated with TUR followed by BCG instillation." (PMID 29861872, 2018). "CD163, indicative of M2-polarized macrophages, was also upregulated and correlates with tumor progression and metastasis; in bladder cancer, high CD163 expression predicts worse survival." (PMID 41179298, 2025). "Bladder cancer: Like in other cancer types, also in bladder cancer, CD163+ TAM infiltration was analogous to histologically advanced disease." (PMID 39451197, 2024). "Sulfatase 2 promoted bladder cancer development by promoting M2 macrophage polarization via CD163 upregulation downstream of the JAK2/STAT3 pathway." (PMID 39451197, 2024). "The results of the analysis of the Kaplan–Meier plotter cancer database revealed that the OS of patients with bladder cancer was significantly inversely correlated with CD163 levels." (PMID 38750006, 2024). "Studies have shown that VEGFA can affect the infiltration of CD163+ TAM in bladder cancer, and the changes in VEGF receptor expression are linked to the disease staging and recurrence of bladder cancer." (PMID 36741702, 2022). "CD163+/CD206+ mono-macrophages in bladder cancer microenvironment are abnormally elevated, and these cells are closely related to tumor progression." (PMID 34803459, 2021). "Bladder cancer tissue samples and paracarcinoma tissues samples were collected, and the expression of CD163+ cells in tumor tissues was observed." (PMID 34803459, 2021). "It is prompted that CD45+CD14+CD163+ mono-macrophage subset is significantly increased in bladder cancer microenvironment, which is one of the characteristics of tumor immune microenvironment." (PMID 34803459, 2021). "The expression proportion of CD45+CD14+CD163+ mono-macrophage subset in bladder cancer tissue (n = 8) was significantly higher than that in adjacent normal tissues (n = 3, 67.88 ± 7.2% vs. 27.05 ± 11.18%, P = 0.001)." (PMID 34803459, 2021). "Macrophage traits in cancer cells, defined by CD163-expression, have been reported for several tumor types, among others renal cell carcinoma, breast, colorectal, and bladder cancers." (PMID 30915533, 2019). "we systemically reviewed and analyzed the prognostic value of TAMs identified by CD68 or CD163 biomarker in bladder cancer patients." (PMID 29861872, 2018). "Current study is the first systemic review and meta-analysis to evaluate the prognostic value of CD68+ and CD163+ TAMs in bladder cancer." (PMID 29861872, 2018). "Our results suggested the elevated density of CD163+ TAMs predicted poor RFS in bladder cancer patients." (PMID 29861872, 2018). "In addition, the CD163 expression levels were significantly correlated with the pathological stage of bladder cancer in the GEPIA website analysis." (PMID 38750006, 2024). "Moreover, SKA3 expression was positively correlated with gene markers of M2 macrophage such as MRC1 and CD163 in bladder cancer." (PMID 35546682, 2022). "By collecting bladder cancer tissue samples, the expressions of CD163+ cells and related membrane molecules in the mono-macrophage subset were analyzed, and the relevant mechanism and clinical significance of how this mono-macrophage subset exerted biological function were discussed." (PMID 34803459, 2021). "However, TAMs detected by CD163 are significantly correlated with poor RFS in bladder cancer patients (HR = 1.54, 95% CI = 1.16–1.92)." (PMID 29861872, 2018).
bladder cancer (continued). "However, our results indicated that elevated CD163+ TAMs density could predict poor RFS in the bladder cancer patients after TUR therapy." (PMID 29861872, 2018). "we co-cultured Si-con or Si-DYM bladder cancer cell lines with M0 macrophages to detect tumor markers of CD206, CD163 and CD86 macrophages." (PMID 35769470, 2022). "In bladder cancer tissue, the expression rate of CD40 in CD45+CD14+CD163- mono-macrophage subset was significantly lower than that in CD45+CD14+CD163+ mono-macrophage subset." (PMID 34803459, 2021). "However, TAMs detected with CD163 could serve as a prognostic marker for bladder cancer patients." (PMID 29861872, 2018). "In addition, SKA3 expression in bladder cancer was significantly correlated with M2 macrophage markers, including MRC1 and CD163, and Th2 cell markers, including CCR3 and IL-4." (PMID 35546682, 2022). "Immunohistochemistry (n = 55) was used to detect Chemokine (C-X-C motif) ligand 8 (CXCL8), CD163 (a TAM marker), Matrixmetalloproteinase-9 (MMP-9), vascular endothelial growth factor (VEGF), and E-cadherin in cancerous and adjacent tissues of bladder cancer patients." (PMID 32201645, 2020). "While BMP4 has been shown to induce M2-polarization of macrophages in bladder cancer, we did not observe significant differences in CD68+ or CD163+ macrophage levels between BMP4low and -high PDAC (TC: p = 0.85; TF: p = 0.52)." (PMID 40826447, 2025). "In this meta-analysis, 11 out of the 13 included studies analyzed the role of TAMs in bladder cancer with CD68 marker, in combination with or without CD163 marker." (PMID 29861872, 2018).
endometriosis (19 papers, 2018 to 2025). The growth of functional endometrial tissue in anatomic sites outside the uterine body. "The areas under the ROC curves (AUCs) of CD8+ T cells and CD163+ macrophages were 0.727 and 0.833, respectively, which indicated that CD8 and CD163 were potential diagnostic markers for endometriosis." (PMID 34539624, 2021). "Pathogenic DAMs associated with endometriosis progression express multiple markers including CD163 and CD206, which may be targets for targeted therapies." (PMID 40679648, 2025). "Consistent with our previous reports, we identified a predominant M2 phenotype (CD14+/CD163+) in the peritoneal fluid of patients with endometriosis." (PMID 40723209, 2025). "When it comes to the eutopic endometrium of endometriosis patients there are fewer “wound-healing” marker CD163+ Mφs and increased CCL2, indicating greater monocyte influx." (PMID 39791759, 2025). "CD163+ cells showed a significant increase (p-value<0.05) in healthy mice and mice after therapy compared to mice with endometriosis." (PMID 39253270, 2024). "The endometriosis related peritoneal macrophages towards to M2-type, manifested by hypersecretion of IL-10 and decreased phagocytosis, and the increase of CD163." (PMID 36263059, 2022). "Flow cytometric analysis showed that the abundance of CD68+CD86+ cells was lower than that of CD68+CD163+ in endometriosis-related peritoneal cells." (PMID 36263059, 2022). "The expression of CD163 in peritoneal macrophages in patients with endometriosis is increased, with the overexpression of MAPK, which can promote the M2-type polarization of macrophages and reduce their ability to phagocytose ectopic endometrial cells." (PMID 36263059, 2022). "The AUCs of CD8+ T cells and CD163+ macrophages were 0.727 and 0.833, respectively, which indicated that CD8 and CD163 were potential diagnostic markers for endometriosis." (PMID 34539624, 2021). "We found that CD8+ T cells and CD56+ NK cells were higher in the eutopic endometria of women with endometriosis than in the endometria of normal controls, while CD163+ macrophages were lower in the eutopic endometria." (PMID 34539624, 2021). "We found that both the MΦ1 (CD80+/CD163−) and mixed MΦ1/MΦ2 (CD80+/CD163+) subtypes were significantly decreased in women with endometriosis, while the MΦ2 (CD80−/CD163+) subtype was significantly increased." (PMID 32572831, 2020). "Immunohistochemical staining analysis showed a significantly decreased intensity of CD163+ macrophage staining in the presence of serum from endometriosis patients after preincubation with SB431542." (PMID 30276219, 2018). "Preincubation with the Smad2/Smad3 inhibitor SB431542 resulted in a decrease in the percentage of CD163+ cells, which was only observed in macrophages treated with serum from endometriosis patients." (PMID 30276219, 2018). "Compared with that in controls, the percentage of CD163+ macrophages in endometriosis patients increased in response to LPS stimulation." (PMID 30276219, 2018). "On the other hand, neutralization of IL-6 with antibody decreased the expression of CD163 and IL-10 in macrophages in an endometriosis condition, reflecting prevention of macrophage polarization toward an M2 phenotype." (PMID 30276219, 2018). "Conversely, endometriosis showed a dominant M2 profile (CD14+/CD163+), elevated intracellular mTOR and AKT expression in both TAMs and epithelial cells (p < 0.01), and significantly higher ascitic ROS and free iron levels (p = 0.047 and p < 0.0001, respectively)." (PMID 40723209, 2025). "CD163+ macrophages (TAMs) have a key role and may contribute, in collaboration with Tregs lymphocytes, to endometriosis growth and the development of EAOC." (PMID 37569458, 2023).
endometriosis (continued). "In clinical samples (n = 40), we found that the proportions of CD8+ T cells and CD56+ NK cells were significantly higher in the eutopic endometria of women with endometriosis than in the endometria of normal controls, while the proportion of CD163+ macrophages were lower in the eutopic endometria." (PMID 34539624, 2021). "Furthermore, our results confirm that macrophages are quantitatively the major cell population found in the PF of endometriosis patients, with significantly increased M2 activation (CD163+/CD206+), especially in patients with mild to moderate disease." (PMID 31907005, 2020). "In a rhesus macaque model of endometriosis, lesions were highly infiltrated by CD163+ macrophages." (PMID 32038499, 2020). "In addition, the mRNA levels of CD86 and CD163 as well as the cytokine IL-12 were significantly higher in macrophages treated with serum from endometriosis patients than in those treated with serum from normal controls." (PMID 30276219, 2018). "Similarly, immunohistochemical staining analysis showed a significantly increased intensity of CD163 staining in macrophages treated with serum from endometriosis patients compared with that in macrophages treated with serum from controls." (PMID 30276219, 2018). "Interestingly, we observed that LGR5+ cell percentage overexpressing CD163 (anti-inflammatory marker) was higher in healthy endometrium, suggesting that in endometriosis, endometrium presents a more pro-inflammatory phenotype that likely leads to poor obstetric outcomes." (PMID 30577586, 2018). "Studies show that women with endometriosis have increased populations of CD8+ T cells and CD56+ NK cells, alongside a decrease in CD163+ Mφs in their eutopic endometrium." (PMID 39791759, 2025). "In a clinical study of adolescent endometriosis, one-year progestin treatment increased the number of CD206+ monocytes (P < 0.001) but decreased the number of CD163+ monocytes (P = 0.017)." (PMID 40630963, 2025). "High expression of CD163 and CD206, required in scavenging of hemoglobin with iron transfer into macrophages, is also registered in patients with endometriosis." (PMID 32751735, 2020). "The ratio of CD163+/CD86+ macrophages was elevated in endometriosis patients, especially in patients with advanced endometriosis (stages III-IV), who had a significantly higher ratio of CD163+/CD86+ macrophages than those with stage I-II endometriosis." (PMID 30276219, 2018). "Transcriptome analysis of proliferative and early secretory samples from endometriosis and healthy women has revealed increased frequencies of CD56+ NK and CD8+ T subsets in ectopic endometriosis and significantly reduced frequencies of CD163+ macrophages." (PMID 35720413, 2022). "Therefore, we examined the distribution and abundance of the MΦ2a (CD80−/CD163+/CD206+) and MΦ2b (CD80−/CD163+/CD86+) subtypes in controls and endometriosis in the CD14+low/CD68+low and CD14+high/CD68+high subpopulations." (PMID 32572831, 2020). "In our study, we found that the serum of patients with endometriosis could induce higher percentage of CD163+ macrophages and upregulate mRNA levels of CD86, CD163, and IL-12." (PMID 30276219, 2018). "Similarly, after preincubation with SB43154, the mRNA expression levels of CD163 and IL-10 were decreased while CD86 and IL-12 expression was increased in macrophages treated with serum from endometriosis patients." (PMID 30276219, 2018). "Interestingly, in addition to MΦ1 and MΦ2 macrophages, we also identified a mixed MΦ1/MΦ2 subtype that was both CD80 and CD163 positive and present in the PF of both women with and without endometriosis (top)." (PMID 32572831, 2020). "Women with endometriosis have more endometrial macrophages that express lower levels of the “wound-healing” marker CD163 compared to women without disease, however the exact mechanisms behind these alterations are unknown." (PMID 32038499, 2020).
endometriosis (continued). "In addition, the expression levels of CD163 mRNA and CD86 mRNA as well as cytokine IL-10 mRNA were not significantly different between the two groups, whereas the expression of IL-12 mRNA in the peritoneal macrophages of endometriosis patients was decreased, as compared with that in control samples." (PMID 30276219, 2018).
fibrosis (19 papers, 2016 to 2025). the formation of excess fibrous connective tissue in an organ or tissue in a reparative or reactive process. "Consist with our results, previous studies have also demonstrated that Ym-1+, CD206+, or CD163+ macrophages were increased and had the potential effect on liver inflammatory changes in different liver inflammation and fibrosis animal models." (PMID 29497376, 2018). "Moreover, the CD163+ macrophages decreased in the AALD fibrosis group, indicating decreased M2 polarization in this model." (PMID 35336043, 2022). "Fibrosis and HCC: Our RNAseq analysis of the livers from Efcab4b−/− mice exhibit downregulation of the macrophage marker CD163, the CD44 antigen and Lymphocyte antigen 96 (Ly96) and upregulation of beta-1, 4-galactosyltransferase 1 (B4GALT1)." (PMID 40034259, 2025).
lymphoma (19 papers, 2016 to 2025). A malignant (clonal) proliferation of B- lymphocytes or T- lymphocytes which involves the lymph nodes, bone marrow and/or extranodal sites. "Another study in diffuse large B cell lymphoma revealed that SUV39H1 upregulated CD86+ and CD163+ tumor–associated macrophages, suggesting a mechanism for lymphoma progression." (PMID 40059829, 2025). "Both FCGR2A and CD163 have been linked to lymphoma and leukemia; they have been studied as diagnostic and prognostic biomarkers." (PMID 37653176, 2023). "In adult T-cell leukemia/lymphoma, CD163-positive TAMs have been associated with poor prognosis." (PMID 41239536, 2025). "In recent years, several studies have demonstrated the roles of TAMs and CD163 in the pathogenesis of hematopoietic malignancies including T-cell leukemia/lymphoma, acute myeloid leukemia, and classical Hodgkin lymphoma." (PMID 38474108, 2024). "MYD88, CD79B, and other NF-κB-pathway-related mutations promote IL-10 expression by lymphoma cells, and IL-10 has also been found to express in CD68+ and CD163+ tumor-associated macrophages by double immunostaining analysis." (PMID 36644235, 2023). "Compared with benign lymph nodes, and consistent with the extent of mono/mac expansion observed in lymphoma-bearing mice, an approximately 5-fold and 2-fold increase in CD163− and CD163+ LAM densities, respectively, were observed in PTCL lymph nodes." (PMID 36970721, 2022). "As for the Iba1 and MAC387 markers, the highest number of CD204 and CD163 immunolabeled cells was observed in high-grade lymphomas." (PMID 34438760, 2021). "A number of studies have reported that higher percentages of CD163+ tumor-infiltrating macrophages were significantly correlated with the poor clinical course of lymphoma." (PMID 29695237, 2018). "Spearman correlation analysis indicated a significantly positive correlation between monocyte count in blood and CD163 scores in lymphoma tissues (p=0.002)." (PMID 28036275, 2017). "Alternatively, we hypothesized that it may depend on CSF1/CSF1R pathway activation, as in solid cancers and lymphoma, which was confirmed by the abrogation of CD163 expression induced by AML CM supplemented with GW2580 or PLX3397." (PMID 34771453, 2021). "To further determine whether CD14 expression is only present in a subset of Mo/MΦs, we also stained lymphoma sections for CD163, a high-affinity scavenger receptor also expressed on Mo/MΦs." (PMID 31611550, 2019). "High-grade lymphomas showed a greater number of CD204+ and CD163+ cells and recently recruited MAC387+ macrophages." (PMID 34438760, 2021). "In in vitro coculture systems with adult T-cell leukemia/lymphoma (ATLL) cells and macrophages, the M2 macrophage marker CD163 was strongly induced by direct contact with ATLL cells, and CD163 knockdown in macrophages significantly suppressed ATLL cell growth." (PMID 27783989, 2016). "Furthermore, NLCs generated in vitro from patients exhibited varying proportions of mature CD163+ NLCs, which correlated with the prognosis of both CLL and aggressive lymphomas." (PMID 39594776, 2024). "Whereas the precise mechanism by which human myeloid cells promote lymphoma growth in HIS-MITRG mice remained unclear, we observed that the tumor-infiltrated macrophages in the CDX model expressed the M2-like macrophage marker CD163 at a high level." (PMID 38162643, 2023). "Regarding the immunohistochemical characterization of the TAM, high-grade lymphomas showed the highest number of Iba1 positively immunolabeled cells, together with higher amounts of recently recruited (MAC387+) and M2 macrophages (CD204+ and CD163+)." (PMID 34438760, 2021). "In addition to CD68 and CD163, S100A9, CCR2, CD32, CD36, and Slan were also critical in the characterization of lymphoma‐specific tumor macrophages." (PMID 33135337, 2020).